ARPC2 (actin related protein 2/3 complex subunit 2)
Diseases named in the same sentence as ARPC2 in open-access papers (continued):
Sharing a sentence is not in itself a finding about the gene and the disease.
tumor (continued). "Thus, we further examined the correlation of ARPC2 with the TME and immune cell infiltration to examine the role of ARPC2 in tumor immunity." (PMID 35733852, 2022). "To investigate whether S-Benp could reach and bind to ARPC2 in cancer cells and tumor tissues, we examined the intracellular localization of S-Benp using Cy3 fluorescence molecules and confocal microscopy." (PMID 36558913, 2022). "Genetic alterations and DNA methylation in tumor tissues may contribute to the aberrant expression of ARPC2." (PMID 35733852, 2022). "Furthermore, we validated that S-Benp colocalized with ARPC2 in cancer cells and directly bound to ARPC2 in tumor tissues using Cy3-conjugated S-Benp according to CETSA." (PMID 36558913, 2022). "Overall, it can be concluded that ARPC2 may promote tumor progression, thereby contributing to the poor prognosis of ACC, KIRC, KIRP, LIHC, and UCEC." (PMID 35733852, 2022). "In addition, the Cy3 signal was mostly colocalized with ARPC2 within the AsPC-1 tumor tissues obtained from the Cy3-Benp-injected mice." (PMID 36558913, 2022). "As one of the subunits of Arp2/3, ARPC2 also promoted tumor development and progression." (PMID 28694563, 2017). "Moreover, we found a significant correlation between ARPC2 expression and tumor immunity in HCC." (PMID 35733852, 2022). "A negative association was observed between ARPC2 and tumor purity, indicating that ARPC2 upregulation in cancer tissues may promote the infiltration of immune and stromal cells in the TME." (PMID 35733852, 2022). "Moreover, in clinical tissues, ARPC2 was associated with tumor size, lymph node invasion, and tumor stage but not with patients' age, gender, or tumor grade." (PMID 28694563, 2017). "Our results provide insights into the expression patterns and clinical significance of ARPC2 pan-cancer and into the relationship among ARPC2 expression, TME, and tumor immunity." (PMID 35733852, 2022). "Considering that the clinical tumor stage (T stage), pathological TNM stage, and histological type were prognostic factors for most cancers, we compared the ARPC2 expression levels in patients with different stages and histological types." (PMID 35733852, 2022). "Functionally, ARPC2 silencing in HCC cells significantly inhibited cell proliferation, migration, and invasion, while the overexpression of ARPC2 promotes tumor proliferation, migration, and invasion." (PMID 35733852, 2022). "The results showed that the expression of ARPC2 was negatively correlated with tumor purity (Rho = -0.169, p = 1.6e-03), whereas the expression of ACTR3 and APRC5 was irrelevant to tumor purity." (PMID 34307456, 2021). "In contrast, the mRNA levels of tumor suppress genes (PTEN, BAK, and CDH1) were increased significantly after the blocking of ARPC2, which indicated that ARPC2 downregulated them." (PMID 28694563, 2017). "Negative correlations across those tumor types were observed in four target genes (ARPC2, CFL1, PLIN3, RAP1GDS1)." (PMID 39201394, 2024). "Previous work indicates that MEFs subjected to RNAi-mediated depletion of the ArpC2 and Arp2 subunits are viable and remain culturable when generated in a genetic background lacking the p16Ink4a/Arf tumor suppressors." (PMID 36706133, 2023). "Moreover, we focused on the analysis of the correlation between ARPC2 expression and the tumor microenvironment (TME) and tumor immunity in pan-cancer." (PMID 35733852, 2022). "To date, there is no publication that documents the relation between ARPC2 and tumor proliferation or invasion." (PMID 28694563, 2017). "Moreover, ARPC2 was closely related to the TME, tumor immunity, and response to ICIs, which might be a potential therapeutic target for immunotherapy and guided individualized immunotherapy for cancers." (PMID 35733852, 2022).
tumor (continued). "In addition, six genes, KRT18, ARPC5L, ACTG1, ARPC2, EZR, and YWHAZ, were simultaneously enriched in tumors and tumor tissues highly expressing TNFRSF11B, which may enhance pathogenic E. coli focal adhesion, actin filament binding, and cadherin binding, as demonstrated by GO functional analysis." (PMID 34938284, 2021).
cancer (14 papers, 2016 to 2025). A tumor composed of atypical neoplastic, often pleomorphic cells that invade other tissues. "The association of ARPC2 with prognostic and clinicopathological parameters was analyzed in pan-cancer based on the UCSC Xena database." (PMID 35733852, 2022). "We found the expression of ARPC2 was upregulated in most cancer types and associated with poor survival prognosis and unfavorable clinicopathological features." (PMID 35733852, 2022). "In particular, we found the presence of transcripts, such as Cux1 and Arpc2, which variably regulate DNA replication, cell proliferation and motility and Csnk1e, which is implicated in the Wnt/β-catenin pathway, a key determinant in cancer proliferation." (PMID 39061080, 2024). "We found that ARPC2 was significantly associated with ICI-related genes in most cancers." (PMID 35733852, 2022). "ARPC2 represents a subunit of the Arp2/3 complex, controls actin polymerization, and modulates cytoskeletal dynamics favoring cancer cells migration, adhesion, and invasion." (PMID 41373651, 2025). "Recent studies show that inhibiting the Arp2/3 complex subunit ARPC2 can suppress cancer cell migration while sparing normal cells." (PMID 39867911, 2024). "Although targeting ARPC2 modulates Arp2/3 complex activity, its composition varies across different cancers, with differential expression levels of each subunit observed in various tumors." (PMID 39867911, 2024). "Considering the absence of corresponding normal tissues in some cancer types, we integrated the GTEx and TCGA databases, including 15,775 samples, to examine the expression patterns of ARPC2 in the 33 cancer types." (PMID 35733852, 2022). "In a previous study, benproperine (Benp) was identified as a cancer cell migration inhibitor and an inhibitor of actin-related protein 2/3 complex subunit 2 (ARPC2)." (PMID 36558913, 2022). "In this study, we comprehensively explored the expression pattern of ARPC2 in 33 human cancer types and different cell lines based on The Cancer Genome Atlas (TCGA), the Genotype-Tissue Expression (GTEx) database, and the Human Protein Atlas (HPA) website." (PMID 35733852, 2022). "The results indicated that ARPC2 was significantly correlated with immune-related genes in most cancers." (PMID 35733852, 2022). "First, we systematically examined the ARPC2 expression patterns of 33 human cancer types according to TCGA and GTEx databases." (PMID 35733852, 2022). "We also discovered, in most cancer types, the ARPC2 mRNA expression was significantly correlated with the CNV percentage, which was mainly reflected in HNSC, BRCA, and BLCA." (PMID 35733852, 2022). "Our pan-cancer bioinformatics analyses showed that ARPC2 was significantly overexpressed in HCC tissues and was closely associated with OS and DSS in patients with HCC." (PMID 35733852, 2022). "In summary, systematic analyses were performed to explore the expression and prognostic value of ARPC2 in pan-cancers using multiple databases." (PMID 35733852, 2022). "Pearson correlation analysis based on GSCALite showed that the ARPC2 expression levels were positively correlated with the CNV percentage in 28 cancer types." (PMID 35733852, 2022). "In this study, we first analyzed the relationship between ARPC2 expression and 47 immune checkpoint-related genes using expression data from TCGA in 33 cancer types." (PMID 35733852, 2022). "The results of RT-qPCR suggested that the expression of ARPC2 was higher in HCC tissues than that in adjacent para-carcinoma tissues, which was consistent with TCGA results." (PMID 35733852, 2022). "Therefore, our data indicate that S-Benp markedly diminished cancer cell migration metastasis by inhibiting ARPC2-mediated lamellipodia formation." (PMID 36558913, 2022). "However, the expression level and clinical significance of ARPC2 in most cancer types remain elusive, and its biological role remains to be elucidated." (PMID 35733852, 2022).
cancer (continued). "In a previous study, we found that Benp suppressed cancer cell migration through ARPC2 inhibition." (PMID 36558913, 2022). "In addition, the experimental results highlighted the cancer-promoting effect of ARPC2 in HCC, which provided a preliminary foundation for the development of biomarker-targeting therapies in HCC." (PMID 35733852, 2022). "Thus, the Arpc2 floxed Cdkn2a null cells used in our studies present an opportunity to study Arp2/3 complex function in a genetic background that is particularly relevant to preventing the growth of cancer cells." (PMID 36706133, 2023). "Thus, we speculated that the differential enrichment of immune and stromal cells in different cancer types might explain why ARPC2 expression plays a distinct prognostic role." (PMID 35733852, 2022). "Therefore, ARPC2 has been suggested as a potential biomarker for cancer diagnosis and therapy." (PMID 35733852, 2022). "Higher expression of these subunits correlates significantly with poor patient survival and advanced cancer stages, with ACTR3, ARPC2, and ARPC5 showing positive correlations with immune cell infiltration." (PMID 41332982, 2025). "In this study, we used different algorithms to analyze the correlation between ARPC2 expression and TME as well as immune cell infiltration in pan-cancer." (PMID 35733852, 2022). "ARPC2 expression was more closely related to DNMT1, which showed a positive correlation in 19 types of cancer and an inverse correlation in four cancer types, but was less closely associated with DNMT3L." (PMID 35733852, 2022). "ARPC2 expression had a significantly positive correlation with five MMR-related genes in HCC, and significant correlations were found between ARPC2 and at least one MMR-related gene in 29 other cancer types, except for OV and UCS." (PMID 35733852, 2022). "The GSEA results indicated that ACTR3, ARPC2, and ARPC5 are involved in multiple cancer-related pathways that promote the development of HCC." (PMID 34307456, 2021). "The activated memory CD4 T cells, activated dendritic cells, resting dendritic cells, M1 macrophages, and neutrophils were positively associated with ARPC2 in most tumors, whereas naïve CD4 T cells did not correlate with ARPC2 expression in 33 cancer types." (PMID 35733852, 2022). "In addition, ARPC2 expression was positively correlated with MMR-related genes and DNA methyltransferases in most cancer types, indicating that MMRs and DNA methylation might influence the expression of ARPC2." (PMID 35733852, 2022). "Therefore, we further explored the relevance of ARPC2 expression to TMB and MSI in pan-cancer." (PMID 35733852, 2022). "Thus, ARPC2 inhibitors may be good prospective therapeutic agents for cancer treatment without toxicity to normal cells." (PMID 36558913, 2022).
infection (4 papers, 2013 to 2021). The state of being infected such as from the introduction of a foreign agent such as serum, vaccine, antigenic substance or organism. "While the origin of the filaments comprising these rare actin baskets remains unclear, we tested whether mDia1 might be responsible for generating the Tir-associated actin puncta by treating ArpC2 Flox and KO cells with mDia1 siRNAs prior to infection with EPEC." (PMID 30550556, 2018). "These cells were then compared to DMSO-treated ArpC2 Flox control cells during infection." (PMID 30550556, 2018). "For instance, the proteins FMNL3, EPB41L1, SSH2, CORO1B and ARPC2 are detected only in E. ruminantium-infected cells, while in FSCN1 and GC, proteins are under-expressed or inhibited by infection." (PMID 34073568, 2021).
infectious disease (1 paper, 2022). A disorder directly resulting from the presence and activity of a microbial, viral, or parasitic agent in humans. "Interestingly, hub genes from age groups of 0-20 years old and 71-100 years old, namely, ARPC2, UBB, FGB, and FGG, are mostly involved in infectious diseases and the immune system." (PMID 36084955, 2022).
ARPC2 also shares sentences with these, for which no sentence is quoted: Arterial thrombosis (1 paper); colon cancer (1); Pan (1); prostate carcinoma (1); pulmonary fibrosis (1); rectal cancer (1).